HCG11 (HLA complex group 11)
Diseases named in the same sentence as HCG11 in open-access papers (continued):
Sharing a sentence is not in itself a finding about the gene and the disease.
cancer (22 papers, 2019 to 2024). A tumor composed of atypical neoplastic, often pleomorphic cells that invade other tissues. "An in-depth study of HCG11 in different types of malignancies has revealed that the role of HCG11 appears to be inconsistent in cancers." (PMID 36602530, 2023). "Conversely, in non-small lung cancer it was found that sponging of miR-224-3p by the lncRNA HCG11 enhances cancer cell proliferation and inhibits apoptosis." (PMID 35779228, 2023). "In the present study, we found that the lncRNA HCG11, which promotes the progression of other common cancers, also regulates OS." (PMID 34949159, 2022). "It has been established that lncRNAs can sponge miRNAs to regulate specific genes and affect cancer malignant phenotypes, whereas the correlation between miRNAs and HCG11 in NPC remains to be explored." (PMID 35463310, 2022). "A query to the lnc2Cancer database showed that eight of the 14 differential hub lncRNAs (LINC00909, BZRAP1-AS1, C17orf76-AS1, HCG11, MIAT, SNHG5, SNHG15, and TP73-AS1) were associated with various types of carcinomas in previous studies." (PMID 35432537, 2022). "With regard to HCG11, it has been identified to be aberrantly expressed in some cancers and function as an oncogene or a tumor suppressor gene, not including OS yet." (PMID 34518440, 2021). "HCG11 has been verified to act as a tumor suppressor gene in many cancers, including oral squamous cell carcinoma, non-small cell lung cancer, cervical cancer, laryngeal carcinoma, glioma and prostate cancer." (PMID 34518440, 2021). "Upregulation of HAGLROS, PVT1, LINC00160, NEAT1, HCG11, and MCM3AP-AS in cancers were associated with poor clinical outcomes in patients with HCC." (PMID 33050642, 2020). "Serval lncRNAs were found to be associated with cancer metastasis and advanced TNM stage, such as HCG11 and MCM3AP-AS in HCC, and SNHG6 in osteosarcoma." (PMID 33050642, 2020). "For example, miR-224-3p levels elevated in NSCLC were found to increase cancer cell proliferation and inhibit apoptotic processes; sponging of this miRNA by lncRNA HCG11 could prevent the oncogenic functions of miR-224-3p in NSCLC cells." (PMID 37409119, 2023). "LncRNA HLA complex group 11 (HCG11) has been identified in various malignant tumors." (PMID 35697671, 2022). "Long non-coding RNA (lncRNA) HCG11 can regulate various cancers through the ceRNA network." (PMID 34949159, 2022). "LncRNA HCG11 sponges miRNA and participates in regulating various cancers by targeting mRNA." (PMID 34949159, 2022). "However, in some cancers, such as hepatocellular carcinoma and gastric cancer, HCG11 has been validated to be an oncogene." (PMID 34518440, 2021). "LncRNA HLA complex group 11 (HCG11) has been reported to be involved in human cancers." (PMID 32844573, 2020). "The role of lncRNA HCG11 in functioning as oncogenes in some cancers has been investigated." (PMID 33027767, 2020). "However, the effect of HCG11 on cancer remains controversial." (PMID 35463310, 2022). "Among the 19 TSLNRs in this study, only eight (EPB41L4A-AS2, MEG3, LINC-PINT, FTX, HCG11, HAND2-AS1, SNHG5 and TPT1-AS1) have been reported previously to be associated with malignancy, and the potential functions of the other 11 lncRNAs in human cancer remain a mystery." (PMID 30764831, 2019). "Based on the cancer histology data obtained from the UALCAN database, we found that HCG11 was expressed at significantly low levels in BC tissues, and its expression was lower in HR-positive BC tissues than that in HER2-enriched and basal-like BC tissues." (PMID 36602530, 2023). "HCG11 and miR-490-3p can compete with each other and regulate MAP3K9 signaling, providing important clues for understanding the importance of lncRNA–miRNA functional networks in cancer." (PMID 35463310, 2022).
cancer (continued). "Moreover, HCG11 and MDM2 were discovered to reverse the inhibiting effects of miR-579-3p on cancer progression, including inhibiting germination, enhancing cycle retardation, increasing death rate, while repressing motility by rescue assays." (PMID 35697671, 2022). "LncRNA HLA complex group 11 (HCG11), as a common lncRNA, has been identified in various cancers." (PMID 34230221, 2021). "We first filtrated ER lncRNAs with continuous status in multiple cancers (EA samples/ES samples > 2 or <0.5 in at least three cancer types) and obtained six EA lncRNAs (PVT1, PSMD5-AS1, FAM83H-AS1, MIR4458HG, HCP5, and GAS5) and three ES lncRNAs (CTD-2201E18.3, HCG11, and AC016747.3)." (PMID 34222227, 2021). "The regulatory networks controlled by NORAD and HCG11, though showing a set of genes that is not big enough to result in significant functional enrichment, indicate that essential processes in cancer signaling are present." (PMID 33739352, 2021).
tumor (16 papers, 2018 to 2025). "We show that low HCG11 expression is closely associated with larger tumor size and shorter overall survival of OS patients, which indicates that HCG11 is a potential biomarker for OS." (PMID 34518440, 2021). "Low HCG11 level is closely associated with larger tumor size and shorter overall survival of OS patients." (PMID 34518440, 2021). "Correlation analysis showed that HCG11 expression was positively associated with tumor size." (PMID 35463310, 2022). "HCG11 acts as a tumor suppressor and suppresses tumor growth in LUAD by promoting Large Tumor Suppressor Kinase 1 (LATS1)." (PMID 38351139, 2024). "Further, by exploring the potential regulatory mechanisms of HCG11, it was found that HCG11 inhibits tumor growth by regulating the SRSF1/β-catenin cascade in HR-positive BC cells." (PMID 36602530, 2023). "Specifically, HCG11 was verified to inhibit cell proliferation and cell cycle in osteosarcoma and suppress tumor growth via miR-942-5p/IGF2BP2/p27 Kip1 axis." (PMID 36874625, 2023). "Altogether, the current study confirmed the tumor-suppressive properties of HCG11 and illustrated its function in HR-positive BC cells." (PMID 36602530, 2023). "HCG11 expression is downregulated in lung adenocarcinoma tissues which inhibits tumor progression by modulating the IGF2BP2/LATS1 axis." (PMID 36602530, 2023). "Through animal model, tumor size and weight were measured to evaluate the tumor-bearing effect in nude mice, which further proved the oncogenic role of HCG11 in vivo." (PMID 35697671, 2022). "A murine tumor xenograft model was used to investigate the regulatory function of HCG11 in NPC in vivo, and immunohistochemical staining was used to determine the Ki-67 level in tumors." (PMID 35463310, 2022). "According to recent studies, HCG11 suppressed apoptosis to accelerate HCC progression in addition to facilitate neoplasm germination and motility in GC via miR-1276/CTNNB1 axis." (PMID 35697671, 2022). "The percentage of Ki67-postive cells was reduced in HCG11 knockdown tumor tissues, as determined by immunohistochemistry." (PMID 35463310, 2022). "During the establishment of the 19 days, 5-8F cells with HCG11 knockdown showed a decreased growth rate, which was further confirmed by the smaller average volume and lighter tumor weight in the HCG11shRNA group." (PMID 35463310, 2022). "HCG11 expression in resected tumor tissues was significantly downregulated in the HCG11 shRNA group, as detected by FISH." (PMID 35463310, 2022). "HCG11 was highly expressed in NPC tissues and was positively associated with tumor stage, lymphatic metastasis, and poor prognosis." (PMID 35463310, 2022). "In conclusion, the present study proves that HCG11 is downregulated in OS and its low expression is correlated with larger tumor size and poor prognosis of OS." (PMID 34518440, 2021). "Consistent with most of the tumors reported, our data suggest that HCG11 is downregulated and exerts a tumor suppressive role in OS." (PMID 34518440, 2021). "HCG11 negatively regulates cell proliferation, cell cycle, DNA replication in vitro and tumor growth in vivo." (PMID 34518440, 2021). "The tumor growth was suppressed after depletion of HCG11, followed by suppressing Ki67, PCNA and Vimentin expression, increasing TUNEL-positive cells and E-cadherin expression." (PMID 34230221, 2021). "When it comes to molecular mechanisms, we show that HCG11 exerts tumor suppressor roles by raising the p27 Kip1 expression." (PMID 34518440, 2021). "Accordingly, the tumor growth in vivo was significantly restrained by HCG11 overexpression and accelerated by HCG11 knockdown." (PMID 34518440, 2021). "Nevertheless, the set of biological pathways observed for the HCG11 network are closely linked to epithelial-to-mesenchymal transition (EMT), a crucial mechanism for malignant phenotype tumor acquiring." (PMID 33739352, 2021).
tumor (continued). "To investigate the function of HCG11 depletion in the modulation of tumor growth, we detect the effect of HCG11 using AsPC-1 cells subcutaneous xenograft mouse model." (PMID 34230221, 2021). "Together, these results indicate that HCG11 is a negative regulator on OS growth in vitro and in vivo, which is also consistent with the fact that HCG11 level is negatively correlated with tumor size of OS patients." (PMID 34518440, 2021). "We then showed that HCG11 level is markedly lower in patients with tumor size greater than or equal to 5cm." (PMID 34518440, 2021). "The GEPIA database was then used to analyze the lncRNA expression; 3 lncRNAs (DLGAP1-AS1 HCG11 LINC00847) were found to be upregulated in tumor tissues as compared to controls." (PMID 33027767, 2020). "Three lncRNAs (DLGAP1-AS1 HCG11 LINC00847) were significantly upregulated in tumor tissues compared to normal controls." (PMID 33027767, 2020). "Tumor formation in mice proved that HCG11 was negatively correlated with miR-1276 and had positively correlation with CTNNB1." (PMID 31889902, 2019). "Although HCG11 functioned as a tumor inhibitor in these studies, the results of our present study showed that HCG11 was high expressed in GC cells and tissues." (PMID 31889902, 2019). "It is identical to GAS5 and HCG11, which located on chromosome 6q22.2 and was down-regulated in tumor tissues compared with non-tumor tissues in both databases." (PMID 30037351, 2018). "In addition, in HR-positive BC patients, decreased expression of HCG11 was positively correlated with tumor size." (PMID 36602530, 2023). "A xenograft mouse model was used to examine how HCG11 affects tumor growth." (PMID 36602530, 2023). "Both in vitro and in vivo, HCG11 acts as a tumor suppressor in HR-positive BC cells." (PMID 36602530, 2023). "Interestingly, lncRNA HCG11 was found to play a pro-oncogenic or tumor-suppressive role in different tumors." (PMID 34949159, 2022). "Moreover, we found a positive correlation between HCG11 levels and tumor weight, which is consistent with previous results." (PMID 35463310, 2022). "Xenograft model was exploited to detect the effect of HCG11 on tumor growth." (PMID 34230221, 2021). "We observed that knockdown of HCG11 notably suppressed tumor growth." (PMID 34230221, 2021). "Additionally, to explore the effect of miR-579-3p over-expression on the malignant behavior of AsPC-1 cells and on the tumor-promoting effect of HCG11, we artificially over-expressed miR-579-3p and HCG11 in AsPC-1 cells after reviewing relevant literature." (PMID 34230221, 2021). "Moreover, abnormal expression of lncRNA HCG11 was related to tumor size, TNM stage and lymph nodes metastasis in NSCLC patients." (PMID 32844573, 2020). "Moreover, HCG11 expression positively correlated with tumor stage and lymphatic metastasis." (PMID 35463310, 2022). "Additionally, we also illustrated that depletion of HCG11 inhibited the tumor growth in vivo." (PMID 34230221, 2021). "Previously, HLA Complex Group 11 (HCG11), located on the major histocompatibility complex (MHC) region, was found to be abnormally expressed in a variety of tumor cells." (PMID 36602530, 2023). "This study found that lncRNA HCG11 was highly expressed in NPC and promoted tumor progression by regulating MAP3K9 signaling by competitively sponging miR-490-3p." (PMID 35463310, 2022). "All these results insinuated that depletion of HCG11 suppressed the tumor growth by targeting miR-579-3p/MDM2, thereby inhibiting tumor cells proliferation, promoting tumor cells apoptosis and blocking tumor cells movement." (PMID 34230221, 2021). "We observed that low HCG11 expression was positively correlated with the tumor size, but not with age, TNM stage and lymph node metastasis in HR-positive BC patients." (PMID 36602530, 2023). "The findings unraveled that, in comparison to the negative control, overexpression of HCG11 could dramatically reduce the tumor size and weight." (PMID 36602530, 2023).
HCG11 also shares sentences with these, for which no sentence is quoted: gastric tumors (4 papers); allergic rhinitis (1); asthma (1); atherosclerosis (1); colon adenocarcinoma (1); colorectal cancer (1); lung squamous cell carcinoma (1); melanoma (1); non-small cell lung carcinoma (1); ovarian carcinoma (1); type 2 diabetes (1).